PTGER4 (prostaglandin E receptor 4)
Diseases named in the same sentence as PTGER4 in open-access papers (continued):
Sharing a sentence is not in itself a finding about the gene and the disease.
inflammatory breast carcinoma (1 paper, 2011). An advanced, invasive breast adenocarcinoma characterized by the presence of distinct changes in the overlying skin. "Although PGE2 has been shown to inhibit cellular proliferation in certain cell types, blockade of PTGER4 expression inhibits both proliferation and invasion of human inflammatory breast cancer cells." (PMID 21589857, 2011).
intraepithelial neoplasia (1 paper, 2025). A precancerous neoplastic process that affects the squamous, glandular, or transitional cell epithelium without evidence of invasion. "Indeed, about 70% of the mice with gastric lesions had intraepithelial neoplasia, and the overgrowth of Lactobacillus murinus ASF361 correlated with enhanced gastric inflammation and the expression of cancer-related factors, such as TNF-α, Ptger4, and TGF-β." (PMID 41304185, 2025).
laryngeal carcinoma (1 paper, 2020). Carcinoma that arises from the laryngeal epithelium. "Patients with laryngeal cancer and methylated PTGER4 promoters had a relatively short DFS (log-rank test, P = 0.020)." (PMID 31969157, 2020). "For patients with laryngeal cancer with a methylated PTGER4 promoter, the OR was 5.04 (95% CI 1.03–24.70; P = 0.046)." (PMID 31969157, 2020). "A similar correlation was observed for PTGER4 in patients with laryngeal cancer (P = 0.046)." (PMID 31969157, 2020).
lymphocytic colitis (1 paper, 2014). Microscopic colitis characterized by the accumulation of lymphocytes in the colonic epithelium and lamina propria. "Lymphocytic colitis was recently shown to be associated with increased TNFA, IFNG, and PTGER4, and a role for prostaglandin proposed in activating pathogenic lymphocytes." (PMID 24959420, 2014).
malignant glioma (1 paper, 2020). A grade III or grade IV glioma arising from the central nervous system. "We have recently demonstrated that prostaglandins, chiefly prostaglandin E2 (PGE2), enhance TDO2 expression and enzymatic activity in malignant gliomas via activation of the prostaglandin E receptor-4 (EP4)." (PMID 32477324, 2020).
medulloblastoma (1 paper, 2013). A malignant, invasive embryonal neoplasm arising from the cerebellum. "Furthermore, we found PTGER4 to be uniquely over-expressed in the SHH subgroup of medulloblastoma (16-fold, p = 0.02) and this finding replicated what was also seen in the Boston and Heidelberg tumor cohorts." (PMID 24252460, 2013). "It was also over-expressed in “Cluster C” GPCR-grouped medulloblastomas (5.66-fold, p = 0.01), however these tumors fell into the Non-WNT/SHH subgroup and the same pattern of PTGER4 expression was not seen in that subgroup as a whole." (PMID 24252460, 2013). "PTGER4 expression in the SHH subgroup was increased in comparison to its expression in Group 3 and Group 4 tumors (t-probabilities = 1.6e-6, 2.7e-8, respectively), but not WNT tumors, in the Toronto series of medulloblastoma patients." (PMID 24252460, 2013).
pneumonia (1 paper, 2022). An acute, acute and chronic, or chronic inflammation focally or diffusely affecting the lung parenchyma, caused by an infection in one or both of the lungs (by bacteria, viruses, fungi, or mycoplasma.). "The remaining three genes, PTGER4, TNFRSF1A, and LTBR displayed mixed directions of expression relative to the pneumonia risk increasing allele when annotating individual SNPs with eQTLs depending on the tissue considered." (PMID 35768473, 2022).
renal cell carcinoma (1 paper, 2024). "The findings indicated that PTGER4 exhibited low expression levels in cell lines of renal cell carcinoma." (PMID 38605343, 2024).
sarcopenia (1 paper, 2023). Progressive decline in muscle mass due to aging which results in decreased functional capacity of muscles. "A negative trend between appendicular skeletal muscle mass (ASMM) and PTGER4 seems to confirm the impairment of muscle regeneration associated with sarcopenia." (PMID 37629065, 2023). "Healthy subjects at age 25–30 and above 50 years old were characterized by a significantly lower mRNA level of PTGER4 in comparison with all analyzed groups of patients (geriatric control, patients with frailty syndrome and sarcopenia)." (PMID 37629065, 2023). "Patients with sarcopenia were characterized by the highest expression of PTGER4 and CTNNB1 in whole blood samples." (PMID 37629065, 2023). "The negative trend of ASMM and PTGER4 seems to confirm the impairment of muscle regeneration associated with sarcopenia." (PMID 37629065, 2023). "However, the highest median of PTGER4 mRNA level was observed in patients with sarcopenia." (PMID 37629065, 2023). "The differences in expression of PTGER4 between geriatric control and patients with frailty syndrome and sarcopenia were not statistically significant." (PMID 37629065, 2023).
schizophrenia (1 paper, 2014). A major psychotic disorder characterized by abnormalities in the perception or expression of reality. "Significant downregulation of PTGER4 has been reported in brains of patients with schizophrenia." (PMID 24571439, 2014).
synovitis (1 paper, 2021). Inflammation of a synovial membrane. "Expression levels of IL1B, IL6, CXCL8, TNF, PTGS2, and PTGER4 showed significant positive correlation with synovitis score." (PMID 33507995, 2021). "We found that expression levels of PTGS2 and PTGER4 were increased significantly with an increase in the synovitis score." (PMID 33507995, 2021). "Expression levels of IL1B, IL6, CXCL8, TNF, PTGS2, and PTGER4 showed significant positive correlations with synovitis score." (PMID 33507995, 2021).
uveal melanoma (1 paper, 2023). A melanoma derived from melanocytes of the uveal tract. "To verify our computational findings, we tested the mRNA expression level of CCL18, CXCL8, GTPBP1, JAG2, PRELID1 and PTGER4 in uveal melanoma cell lines: M17, M23 and SP6.5 and normal uveal epithelial cell: Um95." (PMID 36597071, 2023).
tumor (170 papers, 2007 to 2026). "Functional annotation revealed PTGER4's involvement in B cell activity, NK cell cytotoxicity, and inflammatory responses, pathways previously linked to immune‐mediated tumour control." (PMID 41284374, 2025). "Given the well‐characterised roles of MMP2 and MMP9 in extracellular matrix degradation and metastatic dissemination, their suppression suggests a mechanistic link between PTGER4 deficiency and impaired tumour invasiveness." (PMID 41284374, 2025). "In our mouse model, loss of the Ptgs2 gene encoding COX-2 suppresses tumor growth to some extent, and the growth-suppressive effects of deleting Ptges or Ptger4 are far more robust, a finding with important translational implications." (PMID 39298269, 2024). "When tested in vitro, Ptges-KO and Ptger4-KO tumor cells were 2- to 5-fold more susceptible to TNF-α–induced killing compared with parental and control EV cell lines." (PMID 39298269, 2024). "Hypoxia has been shown to support the progression of this neoplasm through the Cyclooxygenase 2 (COX2)/Prostaglandin E2 (PGE2)/prostaglandin E receptor 4 (EP4)/yes-associated protein (YAP) axis." (PMID 35870078, 2022). "To validate these data further, we analyzed public databases for the association of the expression of “IL-6, PTGER2, and PTGER4” with aggressive tumor phenotypes." (PMID 31014367, 2019). "The co‐occurrence of high PTGER4 expression and 1p36 deletion suggests a potential compensatory relationship, where the loss of tumour suppressors at 1p36 may be counterbalanced by the upregulation of PTGER4‐mediated tumour‐suppressive pathways, such as immune activation." (PMID 41284374, 2025). "The MTPC panel integrated four diagnostic modalities: methylation biomarkers (PTGER4 and SHOX2), tumor markers (CEA and CYFRA21-1), DNA ploidy analysis, and cytological examination." (PMID 41626161, 2026). "Subsequent machine learning‐based feature selection and refinement identified PTGER4, a G‐protein‐coupled receptor, as a pivotal tumour suppressor." (PMID 41284374, 2025). "Collectively, these findings establish PTGER4 as a pivotal tumour suppressor in KIRC, governing both proliferative capacity and invasive behaviour through the regulation of key oncogenic effectors." (PMID 41284374, 2025). "Analysis of gene expression in our single-cell BCC data revealed several targetable Gαs-coupled GPCRs present in tumor cells, including prostaglandin E receptor 4 (Ptger4), adenosine receptor 2b (Adora2b) and β-Adrenergic Receptors (Adrb1–2), among others." (PMID 40060632, 2025). "To rule out that high levels of PGE2 in the TME directly impair T cell function, we knocked out the PGE2 receptors EP2 (encoded by Ptger2) and EP4 (encoded by Ptger4) in OT-1 T cells, followed by their intravenous injection into RTT tumour-bearing mice." (PMID 39604727, 2025). "Supporting these observations, Transwell migration assays exhibited a significant decline in tumour cell motility upon PTGER4 silencing (p < 0.01), indicative of its role in modulating metastatic potential." (PMID 41284374, 2025). "PTGER4 emerged as a potent tumour suppressor, with high expression correlating with improved survival across independent cohorts." (PMID 41284374, 2025). "The CCK‐8 assay revealed a significant reduction in optical density (OD) values upon PTGER4 silencing (p < 0.05), corroborating its essential role in sustaining tumour cell proliferation." (PMID 41284374, 2025). "Further analysis confirmed that PTGER4 is involved in immune‐related pathways and is often reduced in tumours, supporting its role in slowing cancer progression." (PMID 41284374, 2025). "Given the unexpected robust antitumor effect of Ptger4 deletion in tumor cells, we sought to determine the relative contribution of tumor cell–intrinsic versus –extrinsic EP4 signaling in tumor growth." (PMID 39298269, 2024). "To this end, we employed tamoxifen-inducible Ptger4-KO mice as hosts for s.c. implantation of control EV or Ptger4-KO tumor cells." (PMID 39298269, 2024).
tumor (continued). "To identify other genes and pathways affected by the disruption of PGE2/EP4 signaling, we performed RNA-seq on in vitro–cultured and in vivo–sorted tumor cells and bulk tumors from control, Ptges-KO, and Ptger4-KO cell lines." (PMID 39298269, 2024). "Ptger4-KO tumors had a higher proportion of tumor-infiltrating CD45+ immune and CD8+ T cells compared with the control tumors." (PMID 39298269, 2024). "As with Ptges-KO tumor cells, the rejection of primary Ptger4-KO cells as well as rechallenged control EV tumor cells in cured mice was T cell dependent." (PMID 39298269, 2024). "Dpp4, the gene encoding the CD26 receptor that is necessary for adenosine deaminase activity, was upregulated in Ptger4-KO and Ptges-KO tumor cells." (PMID 39298269, 2024). "At the same time, the findings from Bodipy staining revealed that the presence of neutral lipid droplets within the tumor exhibited varying degrees of reduction subsequent to the upregulation of PTGER4 expression." (PMID 38605343, 2024). "The results revealed that the PTGER4 overexpression group exhibited a reduced rate of tumor growth beneath the skin compared with the untreated." (PMID 38605343, 2024). "Mechanistically, Ptges- and Ptger4-KO tumor cells exhibited altered T and myeloid cell attractant chemokines, became more susceptible to TNF-α–induced killing, and exhibited reduced adenosine synthesis." (PMID 39298269, 2024). "Here, we report that deletion of the Ptger4 gene specifically in tumor cells was sufficient to abrogate tumor growth in hosts where EP2 and EP4 signaling in immune cells was intact." (PMID 39298269, 2024). "In hosts treated with an adenosine deaminase inhibitor, Ptger4-KO tumor cells accumulated adenosine and gave rise to tumors." (PMID 39298269, 2024). "Pharmacological blockade of prostaglandin E receptor 4 (EP4) causes a decrease in MDSCs, reprogramming of macrophage polarization, and increase in tumor-infiltrated T cells, leading to enhancement of antitumor immunity in preclinical models." (PMID 38058393, 2023). "Intriguingly, scRNA-seq analysis indicates that the expression of EP2 (PTGER2) and EP4 (PTGER4) is negatively correlated with patient prognosis in different tumor types (LUSC, BRCA, LIHC, and OV)." (PMID 38022587, 2023). "The receptors PTGER2, PTGER3, and PTGER4 exhibited reduced gene expression in all tumor cells, indicating a reduction in the action of PGE2 on these receptors." (PMID 36678600, 2023). "Hypermethylation in approximately half of all the CpG sites of tumor tissue that underwent PTGER4 methylation exhibited an unfavorable 5-year RFS, PFS, and OS, as indicated by the results of the Cox regression analysis and the Kaplan–Meier survival analysis." (PMID 36142151, 2022). "The hypermethylation of PTGER4 promoter sequences at the CpG_4.5, CpG_15, and CpG_17 sites of primary tumor tissue corresponded to unfavorable 5-year RFS, PFS, and OS." (PMID 36142151, 2022). "Higher methylation levels of PTGER4 were observed in the adjacent tumor-free area than in the primary tumor tissue at the following loci: CpG_3, CpG_4.5, CpG_6.7, CpG_9.10, CpG_11, CpG_13, CpG_15, CpG_16, and CpG_18." (PMID 36142151, 2022). "We further evaluated the sensitivity of the SHOX2, RASSF1A, and PTGER4 methylation panel in plasma in different tumor stages." (PMID 34408226, 2021). "While LMS is relatively rare, it has a very poor prognosis; therefore, we decided to analyze the gene expression of TUBB3 and PTGER4 in 54 primary LMS tumor samples from the TCGA representing conventional and poorly differentiated LMS." (PMID 31635323, 2019). "We found PTGER4 tumours to have increased areas of hypoxia in comparison to WT tumours as indicated by the immunoreactivity for the Hypoxyprobe, pimonidazole, per area of tumour investigated (P<0.001)." (PMID 21589857, 2011).
tumor (continued). "We confirmed elevated PTGER4 expression levels in PTGER4 xenograft tumours compared with WT xenograft tumours by quantitative RT-PCR analysis (P<0.001) indicating that expression of the transgene was maintained in vivo." (PMID 21589857, 2011). "Since we found PTGER4 tumours to have an increased proliferation index and hypoxia, we investigated the molecular mechanism regulating PTGER4 expression and proliferation of PTGER4 cells in vitro and the contribution of hypoxia to this." (PMID 21589857, 2011). "Coincident with enhanced PTGER4-mediated tumour growth we found elevated expression of PTGS2 in PTGER4 xenografts compared with WT xenografts." (PMID 21589857, 2011). "PTGER4 expression is elevated in numerous cancers where it can transduce pathways important for cancer cell survival and tumour progression, such as the Akt, extracellular signal regulated kinase (ERK1/2) and early growth response factor-1." (PMID 21589857, 2011). "For instance, coupling PTGER4‐enhancing agents with immune checkpoint inhibitors could synergistically augment anti‐tumour immunity." (PMID 41284374, 2025). "Tumours with high PTGER4 also had stronger immune cell activity and higher levels of immunotherapy‐related markers, suggesting they may respond better to immune‐based treatments." (PMID 41284374, 2025). "In vitro functional assays further substantiated the tumour‐suppressive role of PTGER4." (PMID 41284374, 2025). "Furthermore, EdU incorporation assays demonstrated a pronounced decrease in proliferating tumour cells in the siRNA‐treated group (p < 0.01), reinforcing PTGER4's regulatory influence on cell cycle progression and mitotic activity." (PMID 41284374, 2025). "PTGER4 expression was significantly lower in tumour and normal tissues in most cancer types." (PMID 41284374, 2025). "Additionally, PTGER4‐high tumours exhibited sensitivity to 12 targeted therapies, including MEK inhibitors (Trametinib) and BTK inhibitors (Ibrutinib), suggesting combinatorial therapeutic strategies." (PMID 41284374, 2025). "Lab experiments confirmed that PTGER4 helps block tumour growth." (PMID 41284374, 2025). "Using machine learning, we identified PTGER4 as a potential tumour suppressor." (PMID 41284374, 2025). "Consistently, all 7 mice in the untreated group rejected the KO tumors; by contrast, in 4 out of 7 mice treated with EHNA, Ptger4-KO E10 tumor cells formed tumors by day 11 after implantation that continued growing, albeit with slower kinetics than control tumors." (PMID 39298269, 2024). "Even though both control and Ptger4-KO tumor cells showed an increase in p-SMAD3 protein upon TGF-β and PGE2 exposure, EP4-deficient tumor cells had lower levels of p-SMAD3 compared with the controls, with and without treatment, indicating a deficiency in TGF-β signaling." (PMID 39298269, 2024). "Tumor cell–intrinsic EP4 appeared to be more important in tumor rejection than the same receptors in stromal and immune cells, as Ptger4-KO tumor cells were rejected in both WT and Ptger4-KO hosts, whereas control cells grew in Ptger4-KO hosts, albeit at a slower rate compared with normal hosts." (PMID 39298269, 2024). "We transduced the E0771 tumor cell line to overexpress Ptger4 (E0771 OE)." (PMID 39298269, 2024). "Ptger4-KO tumors produced significantly less adenosine per unit of tumor weight." (PMID 39298269, 2024). "However, there have been few studies on PTGER4 expression in GC, and the detailed biological mechanism of its role in tumor cells remains poorly understood." (PMID 37670284, 2023). "This suggests that a decrease in Ptger4 following VISTA blockade could result in a longer-term anti-tumor effect." (PMID 37762046, 2023). "Both LINC01133 and PTGER4 genes are related with p21, which is a well-known tumor-suppressor gene." (PMID 31856825, 2019). "The PTGER4 tumours displayed an increase in cellular proliferation and increased areas of hypoxia." (PMID 21589857, 2011).